NEAT1 (nuclear paraspeckle assembly transcript 1)
Diseases named in the same sentence as NEAT1 in open-access papers (continued):
Sharing a sentence is not in itself a finding about the gene and the disease.
cancer (continued). "The inhibition of the NEAT1 expression through the CRISPR-Cas9 method increased the sensitivity of radioresistant MDA-MB-231 cells to radiation and decreased their proliferation, the activity of cancer stem cells, and the expression of stemness genes, including BMI1, Oct4, and Sox2." (PMID 32922184, 2020). "Similarly, MALAT1 and NEAT1, other commonly-studied lncRNAs frequently reported to act as miRNA sponges in cancer, are similarly not enriched in number of binding sites." (PMID 31419261, 2019). "Thus, the NEAT1 role in cancer is controversial, and its precise mechanisms have not yet been elucidated." (PMID 31186635, 2019). "However, the clinical trial for cancer treatment, based on NEAT1 studies, has not been reported." (PMID 37752791, 2023). "KEGG enrichment analysis showed that NEAT1 participant in three inflammation-related pathways including, Arachidonic acid metabolism, IL-17 signaling, and NOD-like receptor as well as microRNAs in cancer which may involve in cell proliferation, differentiation, and apoptosis." (PMID 36213831, 2022). "However, the mitophagy induction by NEAT1 in cancer cells has not been studied." (PMID 36430876, 2022). "In addition, NEAT1 was found to inhibit the apoptosis of HemECs, thereby contributing to HA progression, by interacting with miR-361-5p to upregulate the expression of VEGFA, an essential factor in promoting cancer progression by increasing the proliferation and migration of cancer cells 100,101." (PMID 34512157, 2021). "However, in certain types of cancers, such as AML, NEAT1 might act as a tumor suppressor." (PMID 32368311, 2020). "Considering that cancer cells have been reported to increase fatty acid oxidation (FAO) for cell survival due to compromised glucose uptake and ATGL-PPARα signaling have been reported to mediate FAO, we hypothesized that NEAT1 might serve as a means to mediate FAO through PPARα." (PMID 29764424, 2018). "Learning of the expression of Neat1 and formation of paraspeckles in hematopoietic cells will advance the research in the field of normal hematopoiesis and blood malignancy, considering the data on Neat1 in other cancer types and the lack of data in the hematopoietic system." (PMID 29312630, 2017). "However, the role of NEAT1 in other non-studied types of cancer may be further investigated to confirm the role of NEAT1." (PMID 27926523, 2017). "Regardless of stage, MALAT1, NEAT1, CRNDE, and FENDRR consistently exhibited the highest degrees, indicating their widespread and stable regulatory roles in cancer progression." (PMID 40728857, 2025). "Another lncRNA, Nuclear Enriched Abundant Transcript 1 (NEAT1), is upregulated in malignant tissues compared to nonmalignant tissues in several types of cancer, and therefore, it acts as an oncogene that can promote tumor cell progression." (PMID 37706018, 2023). "We plotted ROC curves to determine quantification values of CASC2, NEAT1, and LINC00299 genes, in an attempt to differentiate cancer and noncancer groups patients." (PMID 37706018, 2023). "NEAT1 knockdown reduced proliferation of MCF-7 and MDA-MB-453 cells, unlike miR-101 knockdown promoted cancer cell growth." (PMID 37310654, 2023). "XIST, MALAT1, NEAT1, and LINC00240 up-regulated lncRNA were predicted to bind to hsa-mir-124-3p and promoted the proliferation and metastasis of other cancers by modulating hsa-mir-124-3p, but there are no related studies in CCRCC." (PMID 36531222, 2022).
cancer (continued). "However, whether NEAT1 has positive or negative effect on human cancer is still controversial." (PMID 31186635, 2019).
tumor (419 papers, 2013 to 2026). "Exosomal lncRNA NEAT1 secreted by M2 polarized tumor‐associated macrophages promotes HCC immune escape by recruiting KLF5 and upregulating galectin‐3." (PMID 39720765, 2025). "Increasing evidence indicates that NEAT1 is upregulated in various solid tumors, and its elevated expression is linked with unfavorable prognosis, poor survival, and tumor metastasis." (PMID 40730640, 2025). "Most importantly, CLF modulates the expression of several non-coding RNAs, including MALAT1 and NEAT1, that are linked to tumor cell proliferation, cell migration, and drug resistance." (PMID 41303378, 2025). "NEAT1 is considered an important lncRNA associated with the proliferation or migration of tumor cells." (PMID 39739972, 2024). "CCK8 assays indicated that the increased expression of Cx43 effectively counteracted the inhibition of tumor cell growth and sensitivity to chemotherapy caused by NEAT1 knockdown." (PMID 39453684, 2024). "We found high NEAT1 expression was associated with age (Age(41-60Yrs)-vs-Age(81-100Yrs): 0.089), tumor grade (Grade2-vs-Grade3: 0.0276), race (Caucasian-vs-Asian: 0.0893)." (PMID 38356722, 2024). "After 21 days, Reg2-mutant tumours were significantly larger than controls, providing the strongest support yet that mutations in NEAT1 at the Reg2 position have fitness-altering driver activity." (PMID 37291246, 2023). "The relevance of NEAT1 in tumor–immune cell interaction is highlighted by its high level of expression in exosomes derived from M2-polarized tumor-associated macrophages, which can foster immune evasion." (PMID 37760852, 2023). "To directly evaluate the functional significance of NEAT1 SNVs, we use in cellulo mutagenesis to introduce tumour-like mutations in the gene and observe a significant and reproducible increase in cell fitness, both in vitro and in a mouse model." (PMID 37291246, 2023). "The nuclear paraspeckle assembly transcript 1 (NEAT1) locus encodes two long non-coding (lnc)RNA isoforms that are upregulated in many tumours and dynamically expressed in response to stress." (PMID 35457249, 2022). "Overexpression of NEAT1 promotes tumor development and is associated with poor prognosis in tumor patients." (PMID 35338333, 2022). "Clinical significance of NEAT1 expression displayed its positive association with tumor size, TNM stage, carcinoembryonic antigen (CEA) level, lymphatic metastasis, and presence of distant metastasis of CRC." (PMID 35676702, 2022). "Two long non-coding RNAs (lncRNAs) (MALAT1, NEAT1) were upregulated in both tumor cells and tumor-associated fibroblasts compared to matched normal mesenchymal cells, suggesting remodeling of fibroblasts by AML cells." (PMID 36028490, 2022). "In consequence, miR-128-3p was implicated in the tumor-suppressive effects of NEAT1 knockdown in GBM cell lines." (PMID 34263426, 2021). "NEAT1 drives the occurrence and development of tumors by regulating genes associated with tumor cell growth, migration, invasion, stem-like phenotypes, and chemotherapeutic and radiological resistance." (PMID 33614649, 2021). "A meta-analysis of 1354 patients from 11 studies revealed that NEAT1 expression is indeed significantly associated with poor overall survival, larger tumor size, lymph node metastasis, distant metastasis, TNM-stage, poor differentiation, and invasion depth." (PMID 34680193, 2021). "Despite the fact that NEAT1_2 variant has been considered as a tumour suppressor, the NEAT1 gene is generally considered an oncogene that results in increased chemoresistance." (PMID 33143162, 2020). "NEAT1 is one of the least stable long non-coding RNAs, a presumed tumor promoter, and associated with chemoresistance." (PMID 31717307, 2019).
tumor (continued). "On the other hand, an in vivo study revealed that Neat1 loss provokes global changes in gene expression, resulting in neoplasia promotion." (PMID 31186635, 2019). "LncRNA NEAT1 is proven to be positively associated with CRC tumor differentiation, metastasis, and TNM stages through the NEAT1/miR-495-3p/CDK6 axis." (PMID 31744051, 2019). "In this study, we also identified the oncogene role of NEAT1 in OS, and highly expressed NEAT1 in tumor tissues was associated with high tumor stage and distant metastasis." (PMID 29654165, 2018). "High expression levels of NEAT1 were demonstrated to be associated with poor OS (HR = 1.71, 95%CI: 1.37–2.14, P < 0.001) and tumor progression (III/IV vs. I/II: HR 1.76, 95%CI: 1.40–2.21, P < 0.00001)." (PMID 29026116, 2017). "Subgroup analyses showed that NEAT1 levels were significantly associated with tumor size, TNM stage, and distant metastasis." (PMID 28507281, 2017). "We then analyzed NEAT1 expression for associations with clinicopathological parameters, such as gender, age, smoking, histological type, pathological stage, tumor size (T stage), lymph-vascular invasion (N stage) and relapse." (PMID 29050268, 2017). "Increased NEAT1 expression was found to be moderately associated with tumor TNM stage and progression (III/IV vs. I/II: HR 1.76, 95%CI: 1.40–2.21, P < 0.00001 or II/III/IV vs. 0/I: HR 1.86, 95%CI: 1.39–2.48, P < 0.0001)." (PMID 29026116, 2017). "The in vitro experiments enclosed a contradictory mechanism of NEAT1 variants in tumor development and invasion, which was in accord with the prognostic potential in whole blood." (PMID 26552600, 2015). "Tumor-associated macrophages (TAMs) are known to promote chemoresistance via exosomal signals, but whether exosomal long non-coding RNA NEAT1 contributes to this process is unclear." (PMID 42003906, 2026). "High tumor NEAT1 expression in patients with breast cancer is associated with poor survival." (PMID 41191214, 2025). "Interestingly, results from the TCGA database also revealed that Neat1 levels are associated with tumor metastasis." (PMID 40027195, 2025). "One of the most extensively studied lncRNAs in this context is NEAT1 (nuclear paraspeckle assembly transcript 1), which has been reported to be significantly upregulated in GC tissues and associated with tumor growth, epithelial–mesenchymal transition (EMT), and chemoresistance." (PMID 41244835, 2025). "Low NEAT1 expression levels are associated with high CD8+ T cell infiltration in tumor tissues." (PMID 39539540, 2024). "Consistently, a previous study has verified high expression of NEAT1 in PCa, which is closely associated with tumor progression and poor survival in patients with PCa, but this study failed to clarify the downstream mechanisms or how the NEAT1 action was realized in PCa cells." (PMID 36762032, 2023). "Also, in OC, NEAT1-enriched extracellular vesicles derived from M2-polarised tumour-associated macrophages have been previously demonstrated to favour immune evasion." (PMID 38203310, 2023). "Introduction of tumour mutations at the gene’s 5′ end impacted protein binding, including a significant loss of interaction with the RNA Polymerase II complex mediated by known NEAT1 interactor TAF15." (PMID 37291246, 2023). "While follow-up experiments are necessary for confirmation, it is plausible that editing changes in the differentially edited region identified in NEAT1 using a cluster-based approach may be linked to tumor progression." (PMID 37784060, 2023). "Moreover, high expression of NEAT1 was associated with poorer disease-free survival as well as tumor recurrence in tumor tissues of CRC patients, thereby highlighting NEAT1 as a possible predictive marker for the diagnosis and prognosis of CRC patients." (PMID 35676702, 2022). "Interestingly, two existing variants of NEAT1 serve the opposite effects on the capabilities of tumor growth, apoptosis and invasion." (PMID 35687898, 2022).
tumor (continued). "Another previously identified tumor-suppressing lncRNA related to HNSCC is the nuclear paraspeckle assembly transcript 1 (NEAT1), strongly associated with suppressing cisplatin resistance by modulating several signaling pathways like the Ras-MAPK and the miR-129/Bcl-2 axis in NPC cells." (PMID 35978835, 2022). "Furthermore, NEAT1 long form—and, thus, the paraspeckles—promote skin tumorigenesis by increasing survival of tumor cells expressing mutated KRAS in genetically engineered mouse models." (PMID 33142861, 2020). "High NEAT1 expression was closely associated with tumor size (P=0.006)." (PMID 30154460, 2018). "The results also indicated that NEAT1 expression was highly associated with tumor size (>3 cm vs. ≤3 cm; odds ratio [OR]=2.51, 95% CI: 1.27–4.99; p=0.009), TNM stage (III+IV vs. I+II; OR=4.17, 95% CI: 2.42–7.18; p=0.00001), and distant metastasis (OR=2.73, 95% CI: 1.28–5.79; p=0.01)." (PMID 28507281, 2017). "High NEAT1 expression was associated with tumor progression and poor survival in RCC patients." (PMID 28968960, 2017). "For instance, two studies that measured NEAT1 variants levels but not total NEAT1 expression were excluded, although both studies reported that high levels of NEAT1 variants were related with poor survival in tumor, which was consistent with our conclusion in the present analysis." (PMID 29026116, 2017). "NEAT1 is a possible biomarker for diagnostic purposes, tumor recurrence and prognosis in CRC." (PMID 28108736, 2017). "In recent years, numerous studies have found that NEAT1 is dysregulated in expression in a variety of solid tumours and is involved in tumour cell proliferation, apoptosis, invasion, metastasis and chemoresistance, and is associated with poor prognosis in tumour patients." (PMID 39139172, 2024). "The dysregulation of NEAT1 may be associated with tumorigenesis and promote tumor progression." (PMID 28118609, 2017). "SNHG6 was expressed at the tumor edge and in the pseudopalisading regions around necrosis, but most lncRNAs (Pvt1, SNHG12, H19, Neat1, Malat1, Mir17hg and Ftx) were expressed around the necrotic tumor regions." (PMID 40527978, 2025). "Mechanistically, NEAT1 acts as a molecular reservoir for several tumor suppressor miRNAs such as miR-449b-5p, which de-activate key oncogenic targets such as c-Met and STAT3, which are key players in cell proliferation, invasion, and apoptosis." (PMID 40896358, 2025). "NEAT1‐31 treatment resulted in tumor eradication, as measured by a decreased flux intensity and prolonged survival time." (PMID 40344649, 2025). "According to ROC analysis, for Isfahan patients with GC, NEAT-1 was found to be a good prognostic biomarker and a novel factor for distinguishing samples of control from samples of tumor (P-value 0.0001)." (PMID 41244835, 2025). "The lncRNA NEAT1 is another hypoxia-induced RNA which interacts with the tumor suppressive miR-199a-3p to sustain HCC growth by regulating the miR-199a-3p/UCK2 pathway, suggesting its potential to be a plausible therapeutic target." (PMID 39940704, 2025). "At a 95% confidence level, Neat1 expression was found to be higher in tumor tissues compared to normal tissues." (PMID 40027195, 2025). "Ultimately, in the terminal stage of bone metastasis, exosomal molecules such as miR-375 and lncRNA NEAT1 orchestrate osteoblastic and osteoclastic activity, thereby generating a pre-metastatic niche that supports tumor colonization." (PMID 41357241, 2025).
tumor (continued). "In our previous research, we discovered that overexpression of LncRNA NEAT1 accelerates tumor growth in EC in vivo." (PMID 40018990, 2025). "NEAT1 (Nuclear Enriched Abundant Transcript 1), a nuclear-enriched lncRNA, plays a significant role in promoting tumor progression in NSCLC through mechanisms involving m6A modification and ceRNA." (PMID 40723840, 2025). "M2‐exo treatment markedly inhibited tumor growth, whereas this effect was abolished by NEAT1 downregulation." (PMID 39720765, 2025). "Increasing evidence was provided that NEAT1 is overexpressed in many solid tumors, and higher expression of NEAT1 is correlated with poor survival, recurrence and tumor metastasis." (PMID 39412616, 2025). "NEAT1-silenced exosomes inhibit tumor growth, reduce Ki67 and PD-L1 expression, and increase NKG2D, TNFα, and IFNγ expression in tumors." (PMID 40410719, 2025). "NEAT1 expression is inversely correlated with tumor growth in human breast cancer cells compared with that in normal breast tissues." (PMID 40959280, 2025). "As a result, the lncRNA NEAT1 can discriminate between tumor and control samples in the Isfahan population, making it a great diagnostic biomarker for individuals with GC." (PMID 41244835, 2025). "Through gain- and loss-of-function assays and dual luciferase reporter gene assays, we revealed that the tumor suppressive effects of miR-181a-5p are partially attributed to its downregulation of NEAT1." (PMID 39412616, 2025). "It has been proved that NEAT1 increases the miR-129 gene’s DNA methylation, which inhibits the tumor suppressor miR-129-5p’s expression in breast cancer." (PMID 40730640, 2025). "hsa-miR-378a-3p also exacerbated significant modulatory and silencing effects on the expression of MALAT1 and NEAT1, which are well known to influence tumor progression and inflammatory processes through the propagation of the NF-κB pathway." (PMID 41226545, 2025). "Notable lncRNAs like ANRIL, HOTAIR, MALAT1 and NEAT1 are upregulated by hypoxia and play crucial roles in tumor behavior." (PMID 39940704, 2025). "NEAT1 promotes survival of tumour cells by modulating stress response pathways, such as those activated by hypoxia and DNA damage, allowing the GB cells to withstand the harsh microenvironment and the therapeutic insults of chemotherapy." (PMID 40896358, 2025). "By stabilizing mRNAs, lncRNA NEAT1 contributes to the sustained expression of genes that drive tumor cell proliferation and resistance to apoptosis." (PMID 40231344, 2025). "Starting on day 7, the tumor‐implanted mice were treated with M2‐exo, M2‐exo‐sh‐NEAT1, or saline every 3 days." (PMID 39720765, 2025). "Research indicates a relationship between the downregulation of NEAT1 and METTL3, resulting in diminished methylation of NEAT1 in ccRCC cells, which in turn facilitates tumor cell proliferation and migration." (PMID 40313614, 2025). "Subsequently, we collected different tumor samples and analyzed NEAT1‐31+ macrophages using FACS from 20 patients each." (PMID 40344649, 2025). "Within tumor tissues, Neat1 expression levels were significantly higher in patients with high-stage tumors (stages II-IV) compared to those with low-stage tumors (stage I)." (PMID 40027195, 2025). "Preventing paraspeckle formation by silencing NEAT1 expression in mice sensitized pre-tumor cells to DNA damage-induced apoptosis and impaired skin tumor formation." (PMID 41191214, 2025). "NEAT1 is highly regulated in GB, and its expression is correlated with poor prognosis and increased tumour aggressiveness." (PMID 40896358, 2025). "NEAT1, a polyadenylated lncRNA, has been widely identified as an oncogene that promotes tumor formation and metastasis in various solid malignancies." (PMID 38898019, 2024). "NEAT1 is one of the most common oncogenes in lncRNAs, and its abnormal expression can contribute to the stem cell properties of tumour cells that facilitate the proliferation and metastasis of tumour cells, etc.." (PMID 39139172, 2024).